IL6 (interleukin 6)
Diseases named in the same sentence as IL6 in open-access papers (continued):
Sharing a sentence is not in itself a finding about the gene and the disease.
osteoarthritis (continued). "SDF-1 promotes osteoarthritis cartilage degeneration by activating the hypoxia-inducible factor 1 (HIF-1)/interleukin-6 (IL-6) signaling axis to induce chondrocyte ferroptosis." (PMID 40426865, 2025). "Studies have shown that P. lobata polysaccharides can reduce joint swelling symptoms, decrease the production of serum inflammatory cytokines TNF-α, IL-1β, and IL-6, and slow down inflammation in osteoarthritis (OA) in rats." (PMID 39795251, 2025). "Vitamin D deficiency is associated with increased pain, poorer functional status, and elevated serum levels of TNF-α and IL-6 in individuals with osteoarthritis." (PMID 39940305, 2025). "A study examining the association between IL-6 and central sensitization and pain behavior as a result of osteoarthritis reported the increased expression of spinal IL-6 in an MIA animal model." (PMID 40647239, 2025). "A higher IL-6 expression was found in a group with a more severe phenotype and in a group with osteoarthritis, suggesting that in the advanced stage of the disease, inflammation is more pronounced." (PMID 40142185, 2025). "In spleen tissue of both species hypoxia-responsive DEGs were enriched in terms related to the activation of signaling pathways that are associated with pathologies and damage (“Wound Healing Signaling Pathway”, “Osteoarthritis Pathway”, “IL6-Signaling”)." (PMID 40044716, 2025). "Osteoarthritis (OA) is an age‐related degenerative joint disease, prominently influenced by the pro‐inflammatory cytokine interleukin‐6 (IL‐6)." (PMID 39853717, 2025). "In this context, vitexin, a flavone C-glycoside, demonstrated anti-inflammatory effects via the reduction of both TNF-α and IL-6 levels in rat chondrocytes and in chondrocytes from osteoarthritis patients." (PMID 40076701, 2025). "Numerous studies have further reported elevated levels of IL-6 in the synovial fluid, cartilage, and serum of osteoarthritis patients." (PMID 41019141, 2025). "In patients undergoing osteoarthritis, synovitis develops, inducing effusion of inflamed SF rich in inflammatory factors such as IL-1, IL-6, IL-8, IL-17, and TNF-α." (PMID 40898269, 2025). "Three main pro-inflammatory cytokines that engage in the pathophysiology of osteoarthritis are IL-1β, IL-6, and TNF-α." (PMID 39204123, 2024). "Due to inflammation, NO production increased through the NF-κB signaling pathway, which regulates three pro-inflammatory cytokines of osteoarthritis, including IL-1β, IL-6 and TNF-α." (PMID 39204123, 2024). "Verbascoside at 20 mg/kg doses prevented the development of osteoarthritis in rats by lowering proinflammatory interleukin (IL-1β, IL-6) and tumor necrosis factor (TNF)-α." (PMID 38790677, 2024). "In an experimental study comparing experimentally induced osteoarthritis with control joints in a canine model, a significant elevation of IL-6 was observed in almost all experimental animals at an early stage (3 months) compared to control." (PMID 39472858, 2024). "In synovial fluid and osteoarthritis (OA), IL-6 and TNF-α are the key immune mediators and inflammatory markers." (PMID 39458926, 2024). "Based on 15 studies, they conclude that resveratrol suppresses joint inflammation, marked by reduced pro-inflammatory markers (IL-1, TNFα, IL6, NO), reduces chondrocyte apoptosis and improves cartilage structure in animal models of osteoarthritis." (PMID 39519204, 2024). "Studies demonstrated its anti-inflammatory action by inhibiting IL-6 production and even cartilage extracellular matrix degradation in osteoarthritis." (PMID 38732062, 2024). "It has been reported that IL-6 levels were elevated in patients suffering from osteoarthritis (OA), representing the chronic state, and reached 135.8 ± 224.6 vs. 4.8 ± 0 in healthy controls." (PMID 38732195, 2024). "The results showed that MIA-induced osteoarthritis significantly increased the IL-6 content, enhancing its inflammatory response." (PMID 38786602, 2024).
osteoarthritis (continued). "In particular, CCN1 showed proangiogenic activities in HUVEC cells through binding to αvβ3- and α6β1-integrins, while WISP1 (CCN4) induced IL-6 expression in fibroblasts from synovial membrane from patients with osteoarthritis (OASMFs) through αvβ5-integrin." (PMID 38145300, 2024). "THP-1 cells underwent treatment with β-amyrin, stigmasterol, and the YTPS formulary extract, and individual herbal extracts were evaluated with pivotal cytokines contributing to the progression of osteoarthritis, IL-1β, IL-6, and TNF-α." (PMID 39204123, 2024). "It has been shown that genistein can alleviate LPS-induced damage in mice by down-regulating macrophages, and that it can attenuate osteoarthritis by reducing IL-6 expression in diabetic mice." (PMID 39519252, 2024). "These pathways include the unfolded protein response, the Nrf2-mediated oxidative stress response, the osteoarthritis pathway, the IL-6 signaling, and the aldosterone signaling." (PMID 38500550, 2024). "This study developed a humanised in vitro model to detect osteocyte responses to either interleukin-6, a driver of degeneration and bone remodelling in animal and human joint injury, or mechanical loading, to mimic osteoarthritis stimuli in joints." (PMID 39157681, 2024). "Patients with osteoarthritis exhibit higher levels of inflammatory cytokines IL-1β, IL-6, and TNF-α in the blood, synovial fluid, and cartilage tissue compared to healthy individuals." (PMID 38542192, 2024). "In the pathogenesis of osteoarthritis, miRNA-615-3p was reported to participate in the inflammatory response related to osteoarthritis by increasing the expression of inflammatory cytokines, such as interleukin-1, interleukin-6 and interleukin-α." (PMID 36695327, 2023). "It has been shown that DNMT3A caused DNA hyper-methylation in the IL-6 promoter regions in synovial fibroblasts from osteoarthritis patients and suppressed the IL-6 expression." (PMID 37928907, 2023). "The immunological causes of osteoarthritis are known to involve various cytokines such as B cells, T cells, TNF-α, IL-1, IL-6, and IL-17, among others." (PMID 37623223, 2023). "In summary, our study demonstrated that stimulation with IL-6 and sIL-6R elicits a different molecular and cellular response in osteoblasts from RA patients than cells from patients with osteoarthritis." (PMID 37280473, 2023). "In 2014, Tuija Väänänen reported that the levels of YKL-40 were higher andits concentration was correlated positively with IL-6 in osteoarthritis." (PMID 37114011, 2023). "Induction of an osteoarthritis-like phenotype in the ATDC5 chondrocytes was confirmed by a significant upregulation of il6, mmp13, and colx10a1 and a decrease in col2a1 and acan expression following treatment with IL-1β." (PMID 36814717, 2023). "According to a recent study, CASZ1 plays an anti-inflammatory role in osteoarthritis by downregulating interleukin 6 (IL-6) and tumor necrosis factor-alpha (TNF-α), while preventing apoptosis of chondrocytes, which are unable to regenerate." (PMID 37509718, 2023). "IL6, TNFα, and MMP13, all of which are associated with osteoarthritis (OA) and compromised joint health, have been observed in MT-COMP joints." (PMID 37892235, 2023). "Despite the fact that predominant pro-inflammatory cytokines such as IL-1β, TNF-α, IL-15, or IL-6 are well described in human medicine research, it is not documented which biomarker is the gold standard for evaluating osteoarthritis in animal species." (PMID 37443993, 2023). "LncRNA DILC was identified to regulate the expression of IL-6 in chondrocytes and participated in osteoarthritis." (PMID 37779916, 2023). "Inflammation, which is mainly sustained by pro-inflammatory cytokines such as IL-1b, TNF, and IL-6, plays an important role in osteoarthritis progression." (PMID 37316888, 2023). "Studies have shown that supplementation of 20 mg lutein daily for 3 months resulted in a reduction in plasma IL-6 compared with placebo in early arthrosis patients." (PMID 37408032, 2023).
osteoarthritis (continued). "This corroborates the presence of PVB19 and IL-6 more frequently in individuals with stage 4 osteoarthritis, marked by visible deformities in the affected joint." (PMID 37469492, 2023). "LncRNA CAIF attenuated LPS-mediated IL-6 upregulation via suppression of miR-1246 in osteoarthritis." (PMID 37779916, 2023). "SA alleviated the progression of osteoarthritis (OA) by reducing the levels of IL-1β, IL-6, prostaglandin E2 (PGE2), nitric oxide (NO), and TNF-α in vitro." (PMID 35204088, 2022). "ELISA results demonstrated that exogenous α2MRS significantly inhibited the induction of MMP-13 (p = 0.001), TNF-α (p = 0.005), and IL-6 (p < 0.001) activity in IL-1β-induced human primary osteoarthritis chondrocytes." (PMID 36133821, 2022). "CXCL1 promotes the expression of IL6 in synovial fibroblasts of osteoarthritis and RA patients via the CXCR2, c-Raf, MAPK, and AP-1 pathways." (PMID 35707715, 2022). "Studies showed that glycyrrhizin treatment suppressed IL-1β-induced NF-κB phosphorylation in a mouse model of osteoarthritis (OA), significantly reducing IL-6, prostaglandin E2 (PGE2), nitric oxide (NO) and TNF-α levels." (PMID 35684415, 2022). "Inflammatory mediators, like, IL-6, IL-1β, among several other factors play a crucial role in the pathogenesis of osteoarthritis." (PMID 35600853, 2022). "LncRNA DILC overexpression inhibits IL-6 expression in chondrocytes, thereby alleviating the chondrocytes apoptosis in osteoarthritis." (PMID 35501316, 2022). "Ex vivo RES treated peripheral blood mononuclear cells from osteoarthritis patients produced higher IL-6 levels in a dose-dependent manner." (PMID 35554791, 2022). "Osteopontin has been reported to upregulate the expression of IL-6 and IL-8 cytokines in chondrocytes isolated from human osteoarthritis knee cartilage." (PMID 35909446, 2022). "In addttion, nesfatin-1 stimulates pro-inflammatory mediators, i.e., cyclooxygenase-2, interleukin-6, interleukin-8, and macrophage inflammatory protein-1α in osteoarthritis primary chondrocytes." (PMID 35268222, 2022). "NAMPT secreted by osteoblasts participated in the inflammatory response of osteoarthritis by promoting the release of IL6 and the expression of monocyte chemoattractant protein 1 by osteoblasts." (PMID 36336853, 2022). "In osteoarthritis, many other cytokines (e.g., IL-6, TNF-α, IL-15) also play an important role during the progression of the disease." (PMID 35885038, 2022). "With the progress of the experiment, IL‐6 gradually increased and was significantly correlated to the progression of osteoarthritis in the experimental and control groups of rats." (PMID 35894841, 2022). "TNF-α, and IL-6, both pro-inflammatory cytokines, contribute to cartilage degradation in osteoarthritis and facilitate pain initiation and persistence." (PMID 35941593, 2022). "Previous studies suggested that RORA plays a contributory role in the pathogenesis of osteoarthritis by regulating cholesterol metabolism and IL6/STAT3 pathway." (PMID 36380336, 2022). "Our results revealed that co‐treatment of osteoarthritis chondrocytes with FA and IL‐1β suppressed IL‐1β‐induced production of IL‐6 as well as these inflammatory mediators, indicating dampening of the inflammatory response of the cells." (PMID 34078001, 2021). "Clinical studies confirmed that inflammatory cytokines such as TNF-α, IL-1β and IL-6 were highly expressed in osteoarthritis, which induced chondrocyte apoptosis and destroy articular cartilage." (PMID 34049522, 2021). "Previous studies have proposed that IL6 is one of several pro-inflammatory cytokines present in individuals with confirmed clinical diagnosis of osteoarthritis." (PMID 34428745, 2021). "While no therapies targeting IL-6 pathway inhibitors in individuals with osteoarthritis have been developed, the antibody tocilizumab is an effective treatment in certain conditions when IL-6 levels are increased." (PMID 34627160, 2021).
osteoarthritis (continued). "The beneficial results of PBA application under inflammatory conditions, such as in rat models of permanent ischemic stroke, osteoarthritis, or acute lung injury models, were shown to decrease the release of pro-inflammatory mediators IL-1β, TNFα, and IL-6." (PMID 34656124, 2021). "In the same line, phenolic compounds of EVOO have also been related to downregulation of pro-inflammatory factors as IL-8 and IL-6 in human primary osteoarthritis chondrocytes induced by LPS." (PMID 34440065, 2021). "In particular, IL-1β and TNF-α can stimulate IL-6 expression, and IL-6 is a biomarker reflecting the severity of osteoarthritis." (PMID 34574569, 2021). "The findings on IL-6 expression were corroborated in primary chondrocytes from osteoarthritis patients." (PMID 34209813, 2021). "TNF-α, together with IL-1β, IL-6, and IL-17 are also known to upregulate angiogenic substances, as seen in pathogenesis of osteoarthritis." (PMID 34172047, 2021). "It was reported that avocado and soybean unsaponifiables can restrain osteoarthritis through inhibition of proinflammatory cytokines such as IL-1β, IL-3, IL-6, IL-8, IL-13, and TGF-β; also, they can modulate oxidative damages by repression of ROS production." (PMID 34258301, 2021). "It is interesting to note that functional SNP rs1800795 of the IL-6 gene interacted with SNPs rs1800796 and rs891512 to influence IL-6 (p = 0.037) and sleep (p = 0.038) in non-osteoarthritis patients (controls), also through DD and DA modes, respectively." (PMID 34073132, 2021). "Among many representative mediators, interleukin-6 (IL-6) is one of the best-known compounds characterized by omnidirectional interactions in processes, especially in osteoarthritis occurring in the human body." (PMID 33041790, 2020). "In fact, this increase in IL-6 by administration of 100 mg/kg RSV was also observed in peripheral blood mononuclear cells isolated from patients with osteoarthritis and was dose-dependent." (PMID 33013379, 2020). "Immune cells like activated neutrophils and macrophages can secrete cytokines, such as IL-6 and IL-1β, which amplify the inflammatory process in osteoarthritis." (PMID 32189997, 2020). "IL6 is a mediator of inflammation and immune response, can be detected in synovial fluid, and is expressed in osteoarthritis cartilage, making IL-6 inhibition a potential target for the treatment of KOA." (PMID 33376732, 2020). "A study conducted among patients with osteoarthritis showed that IL-1β, IL-6, IL-8, IL-18, IL-17, IL-22, and transforming growth factor-beta 1 (TGFβ1) were increased in the inflamed synovium tissues compared to the noninflamed tissues." (PMID 32189997, 2020). "In the pathogenesis of the degenerative joint disease, OA, inflammatory cytokines, such as IL-1, IL-6, and TNF-α, promote the synthesis of collagenase and MMPs resulting in the degradation of collagen type II." (PMID 33126603, 2020). "They demonstrated that IL-2, IL-4, IL-6, and IL-10 levels were higher in patients with osteoarthritis compared to the controls." (PMID 32189997, 2020). "In osteoarthritis, IL-6 released by joint tissue will bind to the soluble IL-6 receptor (IL-6R), leading to transsignaling." (PMID 32189997, 2020). "Significant higher levels of IL-6 were released by T98G cells when induced by osteoarthritis patients’ CSF in the presence of LPS." (PMID 32213162, 2020). "Inflammatory factor IL-6 is considered to play an important role in the development of osteoarthritis, which strongly activates the immune system and enhances joint inflammation." (PMID 33041790, 2020). "Our results and records from the Gene Expression Omnibus (GEO) database demonstrate higher levels of IL-6 in patients with RA compared with those with osteoarthritis." (PMID 32547316, 2020). "P2X7R expression was enhanced in osteoarthritis; this led to increased chondrocyte proliferation and release of inflammatory factors such as IL-6 and IL-8." (PMID 32189997, 2020).
osteoarthritis (continued). "It has been reported that knockdown of ASK1 prevented the CTGF-mediated activation of p38 and JNK pathways and inhibited the production of IL-6 in human synovial fibroblasts, a major mesenchymal cells contributed to osteoarthritis." (PMID 31183597, 2019). "Isolated RA synovial fibroblasts have shown reduced expression of p21 relative to osteoarthritis (OA) synovial fibroblasts and adenovirus-mediated delivery of p21 suppresses the spontaneous production of IL-6 and MMP1 in RA synovial fibroblasts." (PMID 31160890, 2019). "In our previous research, the expression levels of IL6 and IL-1β were significantly increased in osteoarthritis synovial membranes." (PMID 31139654, 2019). "Conversely, the addition of NAPA decreased the chondrocyte expression of most of these genes at 24 hours: ADAMTS5, the pivotal matrix-degrading enzymes in osteoarthritis and IL-6 and MCP-1." (PMID 31537813, 2019). "Notch was found to mediated cartilage degradation, fibrosis, and osteoarthritis progression by activating the interleukin-6 (IL-6)-signal transducer and activator of transcription 3 (STAT3) and mitogen-activated protein kinase signaling pathways." (PMID 31640732, 2019). "Overexpression of IL-6 in synovial fibroblasts of osteoarthritis was suppressed through decrease histone acetylation and overexpression DNA methylation." (PMID 31139654, 2019). "We assessed IL-11 expression regulation and the IL-11/IL-6 ratio in osteoarthritis (OA) to better guide clinical therapeutic decision-making." (PMID 30197757, 2018). "Efficacy of gemcabene was investigated in rat models of carrageenan-induced thermal hyperalgesia (CITH), monosodium iodoacetate (MIA)-induced osteoarthritis (OA), and IL-6/IL-6sR-induced inflammation." (PMID 29867478, 2018). "The secretion of G-CSF, VEGF, IL-6, and IL-10 were determined in cell-free supernatants of 3D-cultured synovial explants from three individual osteoarthritis patients." (PMID 29922175, 2018). "It has been reported that IL-6 exhibits higher activity in the joint fluid than in the serum, suggesting an important role in osteoarthritis." (PMID 29673343, 2018). "IL-6 and IL-8 are thought to have an important role in cartilage degeneration and in the pathophysiology of osteoarthritis (OA)." (PMID 30245587, 2018). "In osteoarthritis patients (n = 100) undergoing knee replacement surgery, IL-6 concentrations in synovial fluid [119.8 (193.5) pg/mL, median (IQR)] were significantly higher than those in plasma [3.1 (2.7) pg/mL, median (IQR)]." (PMID 30597965, 2018). "Our goal was to quantify the dose-related effects of meloxicam treatment in the subchondral bone-involving, late phase of mono-iodoacetate-induced osteoarthritis, and to follow the levels of serum IL-6, IL-10 and TNFα, as markers of systemic inflammation." (PMID 28413731, 2017). "Osteoarthritis of the hip joint results in an increase in pro-inflammatory mediators, specifically IL-6, IL-8 and TNF-α in the synovial fluid." (PMID 28468607, 2017). "Osteoarthritis is a degenerative disease of articular chondrocytes and involves several inflammatory pathways and mediators such as IL-6, IL-1β and NO." (PMID 28355351, 2017). "The level of histone H3 acetylation (H3ac) in the IL-6 promoter was significantly higher in RASFs than in osteoarthritis (OA) SFs43." (PMID 28262826, 2017). "Specific recent examples of this: naproxen clinically reduced IL-6 in IL-6-overproducing pheochromocytoma, in sera of patient with osteoarthritis, in subchondral osteoartrthritis osteoblasts, and in osteoarthritis patient synovial cells ex vivo." (PMID 28977822, 2017). "NSAIDs commonly used for the treatment of osteoarthritis decrease IL-6, TNF-alpha and VEGF in the synovial fluid with an improvement in joint pain and function." (PMID 28468607, 2017).